WSPAR (Wnt signaling pathway activating non-coding RNA)
Synonyms: TCONS_00009511-XLOC_004555; lncTCF7; TCONS_00009511
Gene: Long non-coding RNA gene on chromosome 5 (133,913,677 to 133,917,269, forward strand). Ensembl gene ENSG00000249073.
Diseases named in the same sentence as WSPAR in open-access papers:
WSPAR is named in the same sentence as 8 diseases in open-access papers, as found by Europe PMC text mining. Sharing a sentence is not in itself a finding about the gene and the disease. The quoted sentences say what the papers report.
hepatocellular carcinoma (3 papers, 2017 to 2020). A malignant tumor that arises from hepatocytes. "For instance, WSPAR has been reported to promote hepatocellular carcinoma aggressiveness through epithelial-mesenchymal transition." (PMID 32724299, 2020).
pancreatic cancer (1 paper, 2020). "The prognosis significance, biological functions and molecular mechanisms of the factors, including HCAR3, PPY, RFWD2, WSPAR and Amcinonide, should be investigated alone and in combination to facilitate the translational research of pancreatic cancer." (PMID 32724299, 2020).
WSPAR also shares sentences with these, for which no sentence is quoted: tumor (5 papers); cancer (3); liver cancer (3); glioma (2); glioblastoma (1); lung carcinoma (1).